INS (insulin)
Diseases named in the same sentence as INS in open-access papers (continued):
Sharing a sentence is not in itself a finding about the gene and the disease.
type 2 diabetes (continued). "Type 2 diabetes was reported for 70% of patients; 24% of patients received hypoglycaemic agents and insulin therapy." (PMID 33318858, 2021). "In type 2 diabetes, insulin’s inability to inhibit lipolysis and reduce blood levels of free fatty acids contributes to insulin resistance in muscles and the liver." (PMID 34299261, 2021). "Defective insulin secretion by pancreatic beta cells is key for the development of type 2 diabetes but the precise mechanisms involved are poorly understood." (PMID 33652748, 2021). "Upon insulin stimulation, 80% of glucose disposal occurs in skeletal muscle, and muscle mass is correlated with improved insulin sensitivity and protection from type II diabetes and metabolic syndrome in humans." (PMID 33220490, 2021). "This cross-sectional study characterizes trends in ambulatory insulin use, overall and based on insulin characteristics, among adults with type 2 diabetes in the United States from 2016 to 2020." (PMID 34636912, 2021). "Pancreatic beta-cell glucose sensitivity is the slope of the plasma glucose-insulin secretion relationship and is a key predictor of deteriorating glucose tolerance and development of type 2 diabetes." (PMID 32944759, 2021). "More patients with type 2 diabetes were among males than females, as well as more antihyperglycemic, insulin, and antihypertensive users were among males." (PMID 33936384, 2021). "This nine-month New Zealand study differed from ours, in that the participants were people with type 1 and type 2 diabetes, who were using oral glucose lowering medication and insulin and the intervention included graphical feedback of blood glucose readings." (PMID 34674688, 2021). "After development of type 2 diabetes, mice in the insulin group were treated with glargine for 2 weeks." (PMID 34917687, 2021). "For example, insulin-specific antibodies have been reported to be consistently higher in patients with type 1 diabetes compared with patients with type 2 diabetes." (PMID 34174848, 2021). "Several clinical trials in individuals with type 2 diabetes show that high doses of a-LA improve glucose utilization, improve insulin sensitivity and lower fasting blood glucose and insulin concentrations." (PMID 33499039, 2021). "While iatrogenic hypoglycemia is most closely associated with the pathology of T1D, it also impedes optimal glycemic regulation in insulin-requiring patients with other diseases, such as type 2 diabetes." (PMID 34003799, 2021). "In the current study, we thus focused on the insulin secretion in patients with type 2 diabetes and studied its relationship with TYK2PV." (PMID 33799705, 2021). "Results of human studies and clinical trials indicate that resveratrol therapy markedly reduces blood glucose levels and improves insulin action in patients with type 2 diabetes." (PMID 33671110, 2021). "As the frequency of severe hypoglycaemia is relatively low in patients with type 2 diabetes on insulin therapy, it is extremely challenging to establish the relationship between severe hypoglycaemic events and the failure to reach the HbA1c target." (PMID 33532606, 2021). "Inherent to their condition, the participants with type 2 diabetes were characterised by elevated fasting plasma glucose levels (p < 0.001 vs all other groups) and the lowest insulin sensitivity, as exemplified by the GIR during the clamp." (PMID 33258025, 2021). "In contrast, the increased risks of type 2 diabetes in offspring of obese mothers reflects the failure of the pancreatic β cell to compensate during a state of increased insulin demand." (PMID 34108935, 2021). "The results of these studies suggest that endogenous insulin secretion is an independent predictor of unstable GV in outpatients with type 2 diabetes, including in those with severely impaired endogenous insulin secretion." (PMID 33907279, 2021).
type 2 diabetes (continued). "The green tea polyphenol, EGCG (among the major compounds of the extract), significantly reduced the lipid profile and oxidative stress and ameliorated glycemic control and insulin sensitivity in the type 2 diabetes rat model." (PMID 34912223, 2021). "Sedentary behaviour is different from being inactive and, for those with type 2 diabetes, reduces the ability of insulin to uptake glucose from the blood into the body cells." (PMID 34770110, 2021). "Protein tyrosine phosphatase-1B is a well-characterized tyrosine phosphatase, which has been shown to suppress both insulin and leptin signaling pathways and is therefore useful in the treatment of type II diabetes and obesity." (PMID 34434118, 2021). "Type 2 diabetes is characterized by an inability of both insulin and IGF-1 (insulin-like growth factor-1) to appropriately activate their intracellular signaling networks in the endothelium and other tissues." (PMID 34420367, 2021). "“You [staff] didn’t say I was going to be insulin free, or that, but you said it’s (type 2 diabetes), it’s reversible with a certain amount of exercise." (PMID 34111218, 2021). "In our previous IDMPS reports, we reported suboptimal and worsening glycaemic control in patients with type 2 diabetes over a 12-year period, despite increasing prescriptions of insulin." (PMID 33594476, 2021). "For the ‘Biomarker + Genetic model’, sex, WHR, HbA1c, insulin, triglycerides, MetS, type 2 diabetes and GRS were included." (PMID 33429859, 2021). "This facilitates the alteration of an insulin signaling cascade with the resultant effect of insulin dysfunction and, ultimately, type II diabetes." (PMID 34299638, 2021). "IR is a key feature of type 2 diabetes, and virtually all individuals destined to become diabetic show a well-known condition of IR, which is initially overcome by increased beta-cell insulin secretion and plasma insulin concentrations." (PMID 34681797, 2021). "As 80% of the postprandial glucose is transported into muscles by the insulin-stimulated glucose transporter 4 (GLUT4) system, the resistance of muscle to insulin, which is typical in type 2 diabetes, disrupts glucose homeostasis in the whole human body." (PMID 33435419, 2021). "In 2012, an in vitro model mimicking the onset of a type 2 diabetes by stimulating primary human osteoblast with high concentrations of insulin and/or glucose was described." (PMID 33805833, 2021). "Type 2 diabetes patients with TYK2PV should be carefully followed in order to receive the appropriate treatment including insulin injections." (PMID 33799705, 2021). "Using GLP-1RAs versus insulin for type 2 diabetes patients requiring intensified injection therapy in clinical practice is cost-effective." (PMID 33468131, 2021). "Exercise has been found to be an effective treatment for type 2 diabetes, helping to stabilize plasma glucose and improve body composition, insulin resistance, and glycated hemoglobin." (PMID 33274609, 2021). "An examination of impact of using insulin on developing major depressive disorder among people with type 2 diabetes, found a higher prevalence of depression among patients using insulin." (PMID 33803134, 2021). "Type 2 diabetes (T2DM) constitutes a burden to modern society and manifests as a slowly process of gradual loss of glucose taken up by cells in an insulin-dependent way." (PMID 33445738, 2021). "While we focus on the treatment of type I diabetes in this study, anyone taking insulin therapies, including patients with type II diabetes, would benefit from a single administration, dual‐hormone drug product such as this." (PMID 34499434, 2021). "In that same study, all species except S. marinoi showed activity in the protein tyrosine phosphatase 1B (PTP1B) assay, a negative regulator in the insulin signalling pathway that affects those with Type II Diabetes." (PMID 33546180, 2021).
type 2 diabetes (continued). "Type 2 diabetes mellitus (T2DM) is a polygenic disorder which arises mainly when the body cannot utilize insulin effectively." (PMID 34294154, 2021). "GLUT4 is an insulin responsive glucose transporter involved in the several conditions, including type 2 diabetes." (PMID 33859622, 2021). "Asymptomatic cardiac arrhythmias are common in insulin-treated patients with longstanding type 2 diabetes and good glycemic control." (PMID 34952579, 2021). "It has been proposed that type 2 diabetes is a consequence of aberrant lipid metabolism, which supports the concept of interaction between insulin, glucose and FFA homeostasis." (PMID 33815283, 2021). "Of the 335 patients with DM who failed to achieve target HbA1c at 1 year (45.0%), 14 (1.9%) had type 1 diabetes, 202 (27.1%) type 2 diabetes (non–insulin-dependent), and 119 (16%) had type 2 diabetes (insulin-dependent)." (PMID 34934904, 2021). "Subsequent clinical studies during the 2000s showed a glucose-lowering authority of DPP4 inhibitors in humans with type 2 diabetes as monotherapy or in combination with other therapies, i.e., metformin, sulfonylureas, tiazolidinediones, or exogenous insulin." (PMID 33796097, 2021). "Although obesity and type 2 diabetes have a multifactorial origin, it is obvious that insulin and leptin resistance are deeply involved in these pathologies." (PMID 34829598, 2021). "Scientific evidence suggests that plant-based diets can prevent type 2 diabetes by decreasing gastric emptying, improving insulin sensitivity, and increasing insulin secretion." (PMID 34840988, 2021). "Majority of whom (73.7%) were on insulin therapy, and more than half of whom (51.9%) were type 2 diabetes." (PMID 34949164, 2021). "Type 2 diabetes mellitus (T2D) is a metabolic disease characterized by hyperglycemia as a result of impaired insulin secretion and action, estimated to affect 422 million people worldwide." (PMID 33670429, 2021). "Type 2 diabetes is a metabolic disorder featured by impaired blood glucose control, insulin resistance and increased insulin level in blood." (PMID 34535145, 2021). "The pathophysiology of prediabetes is similar to overt type 2 diabetes since two main abnormalities are present in both: insulin resistance and diminished insulin secretion by pancreatic beta cells." (PMID 34831236, 2021). "Evidence suggests that overexpression of the miR-200 family in mice induces pancreatic beta cell apoptosis, subsequently decreasing insulin production and inducing lethal type 2 diabetes." (PMID 34690698, 2021). "In vivo and in vitro studies on insulin resistance fed each other, floating all the possible scientific spaces of the metabolic arena, thus excluding obesity in the pathogenesis of type 2 diabetes." (PMID 33555509, 2021). "Numerous studies have demonstrated the clinical value and safety of insulin pump therapy in type 1 diabetes and type 2 diabetes populations." (PMID 34077674, 2021). "PPARγ is indeed the best-characterized target of the insulin-sensitizers of the thiazolidinedione family used in the treatment of type 2 diabetes, and its use as a therapeutic anti-cancer target is also a matter of debate." (PMID 33846376, 2021). "Lipotoxicity is considered as a major triggering factor in the onset of type-2 diabetes by promoting tissue inflammation and insulin resistance of peripheral tissues." (PMID 35008750, 2021). "For type II diabetes, vitamin D was thought to enhance insulin sensitivity; however, a recent meta-analysis of 18 randomized controlled trials found no benefit of vitamin D supplementation on the markers of insulin sensitivity." (PMID 34836301, 2021). "Due to the increased rates of type 2 diabetes, effective agents that improve insulin sensitivity are urgently needed." (PMID 34203569, 2021). "The potential of reducing BW and improving insulin sensitivity suggests a possible clinical role of PPARγ antagonists in treating obesity and type 2 diabetes." (PMID 34128467, 2021).
type 2 diabetes (continued). "The hypoglycemic effects of PGG obtained in models of both type 1 and type 2 diabetes suggest that this molecule mimics insulin action." (PMID 33919569, 2021). "The patients with LADA had significantly higher HbA1c and lower insulin and C-peptide levels than those with type 2 diabetes did." (PMID 34033299, 2021). "We investigated if mineralocorticoid blockade (Eplerenone) improves insulin sensitivity in individuals with type 2 diabetes compared to healthy controls." (PMID 34350730, 2021). "In type 2 diabetes, two primary pathophysiological mechanisms are involved: (a) Insulin resistance in skeletal muscle and liver, and (b) defective insulin secretion from the beta cells of the pancreas." (PMID 34299261, 2021). "The type 2 or noninsulin-dependent diabetes is reported as the most common form due to abnormal insulin secretion and insulin resistance." (PMID 33763471, 2021). "Understanding the physiological processes that regulate insulin production and secretion is essential for the development of type 2 diabetes-related drugs and treatment." (PMID 33436850, 2021). "These endothelial functions regulate the access of insulin to myocytes, which is correlated to insulin sensitivity, the cornerstone of type 2 diabetes pathophysiology." (PMID 34214082, 2021). "Type 2 diabetes (T2D) is a chronic metabolic disorder primarily characterized by reduced insulin secretion, and its global incidence has been on the rise." (PMID 33668330, 2021). "Intestinal Akkermansia muciniphila is depleted in lean individuals with type 2 diabetes, who have increased 3β‐chenodeoxycholic acid (βCDCA), reduced insulin secretion and fibroblast growth factor 19 (FGF19) expression." (PMID 34085773, 2021). "Our study showed that 10-h TRF reduced body weight and blood glucose and improved insulin sensitivity in overweight patients with type 2 diabetes." (PMID 34620199, 2021). "One of these pathologies, ketosis-prone type 2 diabetes (KPD), is associated with severe hyperglycemia and ketoacidosis on presentation, followed by remission after insulin therapy." (PMID 33905625, 2021). "Hyperglycemia can occur in both obesity and type 2 diabetes due to gluconeogenesis and an impaired ability of insulin to inhibit glucose output from the liver, and to promote glucose transport." (PMID 33738261, 2021). "Our previous and present studies found significant impacts of 1-kestose on insulin levels in both diet-induced obese rats and type 2 diabetes rats." (PMID 34578862, 2021). "The purpose of this study was to investigate the association between insulin therapy and carotid atherosclerotic lesions, including CIMT, carotid plaque and stenosis in real-world settings in Chinese subjects with type 2 diabetes." (PMID 33598483, 2021). "The predominant treatment therapies in people with type 2 diabetes and hospitalization for hypoglycaemia were insulin monotherapy, insulin combined with one glucose‐lowering drug and SU monotherapy." (PMID 34277957, 2021). "Both before and following the MR blockade, the achieved insulin response increased during clamp stage 1 and 2 compared to baseline, in both the individuals with type 2 diabetes and the healthy controls." (PMID 34350730, 2021). "However, as a result, there are increased concentrations of both insulin and glucose, which can cause many unwanted consequences, primarily elevated insulin levels known as hyperinsulinemia, which, over time, contributes to a high risk of developing type 2 diabetes and many heart diseases." (PMID 35056318, 2021). "On the other side, pharmaceutical developments have provided several valid alternatives to insulin for the management of type 2 diabetes (T2D)." (PMID 34774054, 2021). "The NDUFB6 rs540467 SNP modifies PA-mediated changes in insulin sensitivity, body composition and liver fat estimates in type 2 diabetes." (PMID 34659107, 2021).
type 2 diabetes (continued). "The results showed that the apoptosis rate of islet β-cells in the model group of type 2 diabetic mice and palmitic acid-induced cell model group obviously increased, while the level of insulin synthesis and secretion decreased significantly." (PMID 34630099, 2021). "Type 2 diabetes (T2D), the commonest form, arises due to a combination of genetic and lifestyle factors that contribute to defective production of insulin from pancreatic beta cells and resistance to its action in peripheral and central tissues." (PMID 34040588, 2021). "Prevailing evidence suggests that young-onset type 2 diabetes has an accelerated decline of beta cell function, especially in second-phase insulin secretion." (PMID 34671316, 2021). "Adults with type 1 diabetes had a slightly lower mean ASK-12 score (i.e. more optimal medication intake and fewer perceived barriers) than adults with non-insulin-treated type 2 diabetes." (PMID 36994341, 2021). "Type 2 diabetes (T2D) is a condition where insufficient insulin is released to keep the glucose balance in a human body." (PMID 32784626, 2020). "An in vitro multi-enzymatic system was successfully established to synthesize the novel insulin secretion accelerant 4-HIL for the treatment of type II diabetes." (PMID 32731373, 2020). "Lower glycemic index foods that minimize postprandial disturbances in both glucose and insulin are thought to be key in preventing the development and progression of type 2 diabetes and cardiovascular disease." (PMID 33425978, 2020). "In fact, IP7 reduces insulin-dependent activation of Akt by regulating insulin secretion and pleiotropic signaling, as observed in type-2 diabetes (T2D)." (PMID 32992691, 2020). "Type 2 diabetes is characterized by insensitivity to insulin action in liver, muscle, and adipose tissue progressing to impaired pancreatic insulin release and eventually β-cell death." (PMID 32349207, 2020). "Supplementation of ALA improves serum adiponectin levels and insulin sensitivity in patients with type 2 diabetes." (PMID 33144308, 2020). "Blockage of JNK-dependent Con A-induced liver damage and restoring of insulin sensitivity in a mouse model of type 2 diabetes were reported." (PMID 32864980, 2020). "Insulin is the standard drug for the management of type 2 diabetes in pregnancy because it is effective for glycemic control and does not cross the placenta." (PMID 32887578, 2020). "This is the first study to demonstrate the EtOAc extract of S. glabra has good hypoglycemic activity in the type 2 diabetic mouse model via oral route by lowering blood glucose levels and increasing insulin sensitivity in the treated mice." (PMID 33489029, 2020). "Further GO and signaling pathway analyses showed that the predicted targets of these miRNAs mainly focused on DNA binding, mitosis, integrated pancreatic cancer pathway, DNA damage response only ATM dependent, insulin signaling, and type II diabetes mellitus." (PMID 31993806, 2020). "Either mechanism would serve to alleviate pancreatic stress in type 2 diabetes, during which insulin production is often increased due to diminished responsiveness of cells to insulin stimulus." (PMID 32591558, 2020). "In HUNT, LADA patients were less likely to have first-degree FHD but were more often treated with insulin and had lower levels of C-peptide than patients with type 2 diabetes." (PMID 32835373, 2020). "It has been shown that exercise not only improves insulin sensitivity and decreases glucose levels in patients with type 2 diabetes and metabolic syndrome, but also reduces coronary heart disease risk and improves exercise capacity." (PMID 32562386, 2020). "Glyburide is a second-generation hypoglycemic sulfonamide used to treat type 2 diabetes by stimulating insulin secretion by β-pancreatic cells." (PMID 32379777, 2020).